MTA1 (metastasis associated 1)
Diseases named in the same sentence as MTA1 in open-access papers (continued):
Sharing a sentence is not in itself a finding about the gene and the disease.
tumor (continued). "For example, nuclear but not cytoplasmic MTA1 is significantly associated with tumor differentiation (P = 0.000 and P = 0.527, respectively), a novel role demonstrated in the present study." (PMID 24970816, 2014). "In this study, we evaluated the expression of miR-30c in EC tissues and different EC cell lines, further investigated the relationship between miR-30c and MTA-1, validated the tumour suppressor function of miR-30c and explored the regulation of miR-30c in EC cell lines." (PMID 24595016, 2014). "In summary, this study indicates that miR-30c acts as a tumour suppressor by targeting MTA-1 in EC." (PMID 24595016, 2014). "Although both nuclear and cytoplasmic MTA1 are involved in promoting cancer malignancies, such as tumor stage and metastasis, the different subcellular locations and interacting partners may confer different functions." (PMID 24970816, 2014). "The effects of MTA1 depletion on tumor growth in vivo were examined in mouse xenograft model." (PMID 23941622, 2013). "Targeting MTA1 is a promising approach to reduce tumor burden of NPC." (PMID 23941622, 2013). "However, the clinicopathological evidence to support the correlation of MTA1 overexpression with tumor growth is limited." (PMID 23941622, 2013). "Partial inhibition of MTA1 with dietary compounds may be sufficient to slow tumor progression and prevent clinical manifestations of PCa in some patients." (PMID 23469203, 2013). "Furthermore, MTA1-knockdown sensitized cells to these agents resulting in additional reduction of tumor progression and metastasis." (PMID 23469203, 2013). "The average tumor weight was also significantly reduced in MTA1 depleted group (p < 0.01)." (PMID 23941622, 2013). "Thus, the MTA1 gene has been considered to be good target for overcoming tumor metastasis and invasion." (PMID 23227138, 2012). "It has been suggested that UBD expression may be related to other biomarkers used to predict tumour metastasis, such as CD44v6, nm23, MTA1 and matrix metalloproteases." (PMID 20808312, 2010). "MTA1 expression has previously been correlated with more aggressive tumours and may play a role in metastasis and invasion." (PMID 18949081, 2008). "Oesophageal tumours overexpressing MTA1 mRNA (T/N ratio ≥ 2) showed significantly higher frequencies of adventitial invasion (P < 0.05) and lymph node metastasis (P < 0.05), and tended to have a higher rate of lymphatic involvement than the remaining tumours." (PMID 10206283, 1999). "Interestingly, MTA1 expression showed dependence on tumor localization." (PMID 40351767, 2025). "Inhibiting MTA1 may suppress VM, thereby reducing tumor progression and metastasis." (PMID 40565190, 2025). "Furthermore, we found that MTA1 values varied depending on tumor location." (PMID 40351767, 2025). "Likewise, the prostate-specific upregulation of MTA1 did not significantly accelerate tumor progression in the context of the loss-of-function of PTEN, and no metastases were found in either renal or iliac lymph nodes of these mice even by 36 weeks of age." (PMID 38611022, 2024). "Notably, depletion of CUL4B or MTA1 in CXXC5-overexpressing tumors led to a diminished effect of CXXC5 overexpression; consistently, the decrease in tumor growth associated with CXXC5 knockdown could be rescued by the simultaneous silencing of TSC1." (PMID 36539038, 2023). "Based on the known function of MTA1, we hypothesize that the downstream signalling molecules of the FOXP3-MTA1 pathway are cytoskeletal motility-related molecules that mediate tumour metastasis, and this possibility will be explored further in our future experiments." (PMID 34307133, 2021). "Moreover, the MTA1-overexpressing subclones displayed enhanced tumor initiation ability in the nude mice; as low as 1 × 105 MTA1-overexpressing cells could initiate tumors, while the controls failed, indicating that MTA1 promotes oncogenesis in vivo." (PMID 32901005, 2020).
tumor (continued). "Moreover, we have demonstrated that overexpression of MTA1 in vitro could remarkably elevate the capability of spermatogenic tumor cells against heat-induced apoptosis." (PMID 22022494, 2011). "Moreover, because of its highly conserved sequence in humans and mice (96%), MTA1 may provide an ideal antigen to be studied as a ‘self-antigen’ in mouse tumour models with significant relevance for human cancer immunotherapy." (PMID 18949081, 2008). "As expected, MTA1 and COX2 expression were higher in UC tumor tissues compared to control bladder tissues, while E-cad expression was significantly lower." (PMID 40351767, 2025). "An analysis of the relationship between MTA1 and COX2 expression within primary tumor tissues revealed a positive and linear correlation of statistical significance (left)." (PMID 40351767, 2025). "Depending on the cellular context, NuRD can promote or suppress tumorigenesis, and through the complex members MTA1 and MTA2 affect tumor progression and metastasis." (PMID 39696035, 2024). "Specifically, proteins like ATF2, MTA1, ROCK1/2, and CD147 are involved in tumor angiogenesis, while GNA12, EPHA2, and COIA1 promote migration and metastasis." (PMID 38132461, 2023). "In contrast, FTO functions as a tumour suppressor in CRC, which depresses MTA1 expression and reduces its mRNA stability in an m6A‐IGF2BP2‐dependent manner." (PMID 38082402, 2023). "Its components, including MTA1, HDACs, Sal4, and CHD4, are expressed in different cancer types and corroborate the tumor progression and poor prognosis." (PMID 37509346, 2023). "Among the significantly affected immune cells, direct tumor killers, CD8+ T cells and NK cells were enhanced with MTA1 upregulation." (PMID 35350571, 2022). "Previous studies have indicated that MTA1 and MTA2 support tumor progression and EMT, while MTA3 inhibits EMT and cancer metastasis." (PMID 36575438, 2022). "ERα can inhibit the proliferation and invasion of human HCC cells by down-regulating the transcription of MTA1, and the overexpression of MTA1 weakens the proliferation and invasion of HCC cells and tumor formation in vivo by the inhibitory effect of ERα." (PMID 35096574, 2021). "The tumor tissues showed higher JMJD5 and MTA1 expression levels compared with adjacent normal tissues (P < 0.001)." (PMID 32678829, 2020). "Immunohistochemistry was used to analyze the effect of miR-543 on the expression of Ki67, MTA1 and CD31 proteins in tumor tissues by targeting MTA1." (PMID 32410569, 2020). "While we have reported a positive relationship between MTA1 and ETS2 in this study and previously, suggesting a tumor-promoting role for ETS2, the literature evidence remains divided, suggesting both tumor-promoting and tumor-suppressive functions for ETS2." (PMID 31487842, 2019). "In this study, we found that CTL epitopes were capable of inducing tumor cell lysis by specific CTLs, suggesting that CD8+ T cells exhibit reactivity to MTA1 following in vitro peptide stimulation." (PMID 30596107, 2018). "In human colorectal cancer, previous work revealed that MTA1 and MTA2 expression was up-regulated and correlated to tumor aggressiveness." (PMID 28418887, 2017). "We found that expression of MTA1 increased after TACE treatment, especially in tumor periphery, which was accompanied by markedly elevated MVD value, indicating a significant correlation between MTA1 and MVD value." (PMID 28589145, 2017). "In order to further investigate the relationship between MTA1 and prognosis of DTC, all the eligible studies were divided into several subgroups according to the quality of each study and tumor type." (PMID 28570554, 2017).
tumor (continued). "Next, we evaluated response to treatments by measuring the expression levels of MTA1 and HIF‐1α in tumor tissues." (PMID 29024573, 2017). "We detected the expression of MTA1 and hypoxia-inducible factor-1α (HIF-1α) and microvessel density (MVD) value in liver tumor tissues and tumor periphery before and after TACE treatment." (PMID 28589145, 2017). "The clinical features reported for MTA1-overexpressed human HCC revealed a high similarity to the characteristics of the S2 subclass, including large tumor, poor differentiation, early recurrence, and poor survival." (PMID 27323415, 2016). "We observed wk-MTA1dE4 overexpression in the tumor tissues of most woodchuck HCC models, accounting for approximately 50% of the total wk-MTA1." (PMID 27323415, 2016). "Because miR-30c can directly repress the expression of MTA-1, and because MTA-1 is an oncogene in EC, we believe that miR-30c functions as a tumour suppressor by targeting MTA-1." (PMID 24595016, 2014). "MTA1 promotes NPC cell proliferation via enhancing G1 to S phase transition, leading to increased tumor growth." (PMID 23941622, 2013). "In summary, we found that MTA1 knockdown in NPC cells decreases cell proliferation in vitro via the induction of G1 phase arrest and drastically suppresses tumor formation in vivo." (PMID 23941622, 2013). "To assess the effect of MTA1 on NPC growth in vivo, we injected MTA1 depleted C666-1 or CNE1 cells, or their control cells into nude mice subcutaneously, and then monitored tumor growth." (PMID 23941622, 2013). "There were no statistically significant variations in MTA1 expression across the groups with respect to the clinical characteristics, patient age, gender, tumor site, and death incidence." (PMID 40660330, 2025). "PROX1 and MTA1 have the potential to be utilized as predictors of progression and recurrence in SGCs because they are good indicators of LVI, recurrence, distant metastasis, and tumor stage." (PMID 40660330, 2025). "Additionally, exosomal proteins like ATF2, MTA1, and CD147 have been shown to induce tumor angiogenesis under hypoxic conditions." (PMID 38132461, 2023). "Suprisingly, Kaplan–Meier analysis showed a significantly lower disease-free survival in tumor samples without a nuclear expression of MTA1." (PMID 36689059, 2023). "Based on the characteristics of the MTA1-derived immunosuppressive microenvironment, we can further focus on enhancing the tumor-killing effect of CD8+ T cells by interfering with the MTA1 level since it intermediates the interaction between CD8+ T cells and tumor cells." (PMID 35350571, 2022). "Unfortunately, with still unverified mechanisms, macrophages were always lacking in the tumor microenvironment with MTA1 overexpression." (PMID 35350571, 2022). "Histological analysis further indicates that V+E@Gel could effectively inhibit tumor angiogenesis and metastasis by down-regulating the expression of CD34, CD31, MTA1 and TGF-β." (PMID 36145556, 2022). "Additionally, MTA1 expression in tumor tissues from the VDA@Gel group was also reduced by 50% in comparison with the saline group, demonstrating the inhibition of tumor metastasis and vascular disruptive effect of CA4P." (PMID 36145556, 2022). "Histological analysis further proved that V+E@Gel could effectively inhibit tumor angiogenesis and metastasis by down-regulating the expression of CD34, CD31, MTA1 and TGF-β." (PMID 36145556, 2022). "Though miR-421 has been identified to target multiple mRNAs to alter tumor progression, such as FOXO4, MEF2D, and MTA1, whether miR-421 can target PDE7B remains to be uncovered." (PMID 33817314, 2021). "The CRL4B/NuRD(MTA1) complex could also promote cell response to the EMT and CSC‐related pathways, such as hypoxia, Wnt, and Notch, thereby promoting tumor metastasis as well as acquisition and maintenance of stem cell‐like properties." (PMID 34026424, 2021).
tumor (continued). "Furthermore, the mRNA levels of VEGF, MTA1, PEG10 and hTERT in the PRKD3‐knockout xenograft tumours were lower than that in the parental tumours." (PMID 31944568, 2020). "Excessive expressions of N-cadherin, MTA1, MMP-2, and MMP-7 also facilitate tumor metastasis." (PMID 31189744, 2019). "Interestingly, significant differences between SO and RAO were detected in tumor expression of MTA-1 (p = 0.015) and ezrin (0.002) with all RAO samples having high MTA-1 and most SO samples having low ezrin expression." (PMID 32039013, 2019). "Although MTA1-specific T cells can lyse MTA1+ tumor cells rather than normal cells, which express low levels of MTA1, and the body weight of mice in the peptide or protein group was not affected." (PMID 30596107, 2018). "Before TACE treatment, MTA1 was stained in 34 of the 63 HCC samples in tumor tissues, but none of the surrounding liver tumor tissues were stained." (PMID 28589145, 2017). "Moreover, we found significant correlation between MTA1 and HIF‐1α mRNA expression (r = 0.67; P = 0.034) in our own 10 prostatectomy tumor samples obtained immediately after surgery." (PMID 29024573, 2017). "Other clinicopathological variables such as gender, age, tumor size, differentiation or distant metastasis were not correlated with MTA1 expression." (PMID 28570554, 2017). "Here in the study, expression of HIF-1α increased significantly in periphery of necrotic tumor regions and tumor periphery one month after TACE and positive expression sustained two months later, which was in accordance with the pattern of alterations in MTA1." (PMID 28589145, 2017). "Similar to human MTA1 RNA, wk-MTA1 RNA was scarcely detected in the normal liver tissues, and its expression level was much higher in tumor than in nontumor cells in most tissues." (PMID 27323415, 2016). "We also demonstrated that wk-MTA1 played a significant role in WHx-mediated tumor cell invasion and promotion, a function that had not previously been studied in the human HCC cell model." (PMID 27323415, 2016). "In addition, overexpression of MTA1 attenuated ERα-mediated suppression of the proliferation and invasion of HCC cells and tumor formation in vivo." (PMID 26503703, 2015). "Thus the biological relevance of MTA1 to NPC growth and tumor volume need to be further investigated." (PMID 23941622, 2013). "We observed that 48.6% of the specimens expressed high levels of MTA1 in the tumor cell nuclei, while MTA1 was absent or expressed weakly in the nuclei of the adjacent noncancerous epithelial cells." (PMID 22537306, 2012). "In line with the high expression of MTA1, we found LacZ-positive cells in the left axillary lymph node of tumor-afflicted mice." (PMID 22030022, 2011). "However, when it came to the following factors: tumor size, incidence of nodal and distant metastases, TNM clinical stage, and incidence of tumor recurrence, there were a high statistically significant difference in MTA1 expression (P < 0.000)." (PMID 40660330, 2025). "Notably, the MTA1, MTA2 and MTA3 components of the NuRD complex have been shown to play an important role in the ER and HER2 pathways regulating the epithelial-mesenchymal transition (EMT) and tumor cell invasion and metastasis, but they have distinct effects." (PMID 29625565, 2018). "In conclusion, our study highlights a pivotal role for miR-543 as a tumor suppressor in the regulation of CRC cell proliferation and metastasis by targeting KRAS, MTA1 and HMGA2 and suggests that miR-543 may serve as a novel diagnostic and prognostic biomarker for CRC metastasis." (PMID 26968810, 2016). "Down-regulation of MTA1 by RNAi approach led to re-expression of ER alpha in ER-negative breast cancer cell lines MDA-MB-231, and reduced protein levels of MMP-9 and CyclinD1, as well as decreased tumor cell invasion and proliferation, more cells were blocked in G0/G1 stage(P < 0.05)." (PMID 21595884, 2011).
tumor (continued). "MTA1 was found to be over-expressed in all murine tumour cell lines as compared to normal tissues, except the testis, which showed a similar level of expression to tumour tissues (data not shown)." (PMID 18949081, 2008). "Although we did not detect a statistical difference in MTA1 overexpression between primary tumors that developed metastasis and those that did not, matched tumor-metastasis pairs showed a tendency for higher MTA1 in lung metastatic lesions, suggesting that MTA1 might work as a prognostic marker." (PMID 40351767, 2025). "However, there were high statistically significant differences in MTA1 expression when it came to the following variables: tumor size (P = 0.000), the incidence of nodal (P = 0.002) and distant metastasis (P = 0.000), TNM clinical stage (P = 0.000), and the incidence of tumor recurrence (P = 0.000)." (PMID 40660330, 2025). "We overexpressed or knocked down wk-MTA1 in a woodchuck HCC cell line and demonstrated that wk-MTA1 could interact with the WHV X protein (WHx) and play indispensable roles in WHx-mediated NF-κB activation and tumor cell migration- and invasion-promoting activities." (PMID 27323415, 2016). "Functional studies have demonstrated that, unlike MTA1 and MTA2, which predominantly facilitate tumor progression, MTA3 was initially reported to suppress cancer cell invasion and metastasis." (PMID 41584603, 2025). "Limited by the complex interaction and secretion in the tumor microenvironment, we have not yet defined the core chemokine regulation networks between tumor cells, CD8+ T cells and macrophages derived by MTA1." (PMID 35350571, 2022). "Remarkably, protein abundance, but not genomic or transcriptional alterations of YB-1 and MTA1, is predictive of disease recurrence, exhibiting a dose-dependent effect on time to PSA recurrence, an indicator of tumor relapse." (PMID 25797255, 2015). "However, unlike MTA1 and MTA2 which were mainly involved in cancer progression and metastasis, MTA3 possesses both tumor-suppressing and tumor-promoting properties depending on specific cancer types." (PMID 31552166, 2019).